CFTR (CF transmembrane conductance regulator)
Diseases named in the same sentence as CFTR in open-access papers (continued):
Sharing a sentence is not in itself a finding about the gene and the disease.
cystic fibrosis (continued). "Mutations in the CFTR gene lead to reduced or dysfunctional CFTR protein and cause cystic fibrosis, a generalized exocrinopathy affecting multiple organs, but is most notably associated with lung disease." (PMID 28536625, 2016). "Cystic fibrosis is a heritable disorder caused by mutation in the CF transmembrane conductance regulator (CFTR) and characterised by severe pulmonary manifestations." (PMID 26957481, 2016). "The root cause of CF is heritable recessive mutations that affect the cystic fibrosis transmembrance conductance regulator (CFTR) gene and the subsequent expression and activity of encoded ion channels at the cell surface." (PMID 27434588, 2016). "CF is a multi-organ inherited disease, caused by mutations in the CF gene product, the cystic fibrosis transmembrane conductance regulator (CFTR), a cAMP-regulated anion channel." (PMID 27098663, 2016). "While inflammation with aberrant activation of NF-κB pathway is a hallmark of cystic fibrosis, the molecular mechanisms underlying the link between CFTR defect and activation of NF-κB-mediated pro-inflammatory response remain elusive." (PMID 27588407, 2016). "Cystic fibrosis is a complex disorder affecting multiple epithelial organs that is caused by over 2000 mutations in the cystic fibrosis transmembrane conductance regulator (CFTR) gene and remains the most common fatal genetic disease in Caucasian populations." (PMID 27456476, 2016). "Cystic fibrosis is a rare inherited disease, caused by the malfunction of the chloride channel Cystic Fibrosis Transmembrane conductance Regulator (CFTR)." (PMID 27898711, 2016). "The majority of cystic fibrosis -causing mutations in the cystic fibrosis transmembrane conductance regulator (CFTR) lead to the misfolding, mistrafficking, and degradation of the mutant protein." (PMID 27182737, 2016). "CF is caused by mutations of the gene encoding the cystic fibrosis transmembrane conductance regulator (CFTR) which is an anion selective transmembrane ion channel that mainly regulates chloride transport, expressed in the epithelia of various organs." (PMID 27491544, 2016). "Cystic fibrosis is an autosomal recessive disease that arises as a result of defects in the CF transmembrane conductance regulator (CFTR) gene that encodes an ion channel in the apical membrane of epithelial cells." (PMID 27434588, 2016). "CF is an autosomal-recessive disease caused by a loss-of-function mutation in the cystic fibrosis transmembrane conductance regulator (CFTR) gene." (PMID 27193199, 2016). "Due to mutations in the cystic fibrosis transmembrane conductance regulator (CFTR) in CF airways, ion channel abnormalities are observed and the innate and adaptive immune responses are impaired." (PMID 27301427, 2016). "CF results from a mutation in the cystic fibrosis transmembrane conductance regulator (CFTR) gene, which encodes a cell-surface chloride ion channel." (PMID 28035194, 2016). "Cystic fibrosis is a complex disease and it is well recognized that although the principals underlying the genetic and functional defects in CFTR have been identified, two individuals with the same CFTR genotype may follow a different natural history and trajectory of their lung disease." (PMID 26403534, 2015). "Cystic fibrosis is a genetic disease attributable to mutations in the cystic fibrosis transmembrane conductance regulator gene (CFTR)." (PMID 26594334, 2015). "CF is a heterogeneous recessive genetic disorder having characteristics that reveal mutations in the cystic fibrosis transmembrane conductance regulator (CFTR) gene." (PMID 25850012, 2015). "CF is a recessive genetic disorder caused by mutation in the cystic fibrosis transmembrane conductance regulator (CFTR) gene." (PMID 26469863, 2015). "Cystic fibrosis is a heterogeneous multiorgan disease caused by mutations in the CFTR gene leading to misfolding (and other defects) and consequent dysfunction of CFTR protein." (PMID 28031875, 2015).
cystic fibrosis (continued). "In Palestine, mutations in the Cystic Fibrosis Transmembrane Conductance Regulator gene (CFTR) that contributes to the clinical presentation of CF are ill defined." (PMID 26208274, 2015). "CFTR is expressed at the apical surface of human airway epithelia and loss of CFTR function in cystic fibrosis results in mucus accumulation, reoccurring bacterial infections, respiratory inflammation, and declining lung function." (PMID 25879443, 2015). "Cystic fibrosis is an autosomal recessive genetic disorder caused by loss of expression or functional mutations to the cystic fibrosis transmembrane conductance regulator (CFTR)." (PMID 26185359, 2015). "CF is caused by mutations in the gene encoding the cystic fibrosis transmembrane conductance regulator (CFTR)." (PMID 26335336, 2015). "Cystic fibrosis is caused by mutations in the gene encoding the CF transmembrane conductance regulator (CFTR) protein, an ion channel that transports chloride ions across epithelial cell membranes." (PMID 25641878, 2015). "Clevers’s group cultured intestinal (LI) stem cells from CF patients homozygous for the most common cystic fibrosis transmembrane conductance regulator (CFTR) mutations and used CRISPR/Cas-mediated homologous recombination to correct the CFTR locus." (PMID 26762955, 2015). "CF is caused by mutations in the gene encoding cystic fibrosis transmembrane regulator (CFTR), a transmembrane chloride ion channel." (PMID 26217312, 2015). "Loss of function mutations in CFTR cause the fatal inherited disease cystic fibrosis, while overactive CFTR in the GI tract leads to secretory diarrhoea." (PMID 25277268, 2015). "Cystic Fibrosis is a multi-systemic disease resulting from mutations in the Cystic Fibrosis Transmembrane Regulator (CFTR) gene and has major manifestations in the sino-pulmonary, and gastro-intestinal tracts." (PMID 25822311, 2015). "Airway microbiota composition has been clearly correlated with many pulmonary diseases, and notably with cystic fibrosis, an autosomal genetic disorder caused by mutation in the CF transmembrane conductance regulator (CFTR)." (PMID 25853698, 2015). "CF is caused by mutations in the gene encoding the chloride channel “Cystic fibrosis transmembrane conductance regulator” (CFTR)." (PMID 26549988, 2015). "Cystic fibrosis is a fatal autosomal recessive disease which is caused by mutation in the gene encoding the cystic fibrosis transmembrane conductance regulator (CFTR)." (PMID 25617802, 2015). "Cystic fibrosis is caused by mutations in the cystic fibrosis transmembrane conductance regulator (CFTR) gene and remains one of the most frequent lethal hereditary diseases in Caucasian populations." (PMID 25629612, 2015). "Cystic fibrosis is a genetically inherited disease which results in mutations in the cystic fibrosis transmembrane regulator (CFTR) gene." (PMID 25120571, 2014). "CF is caused by mutations in the gene encoding the cystic fibrosis transmembrane conductance regulator (CFTR) protein, which is expressed in airway epithelial cells and acts as a chloride channel activated by cyclic AMP." (PMID 25268127, 2014). "Up to 50% adult patients with cystic fibrosis, a disease caused by mutations in the gene encoding the CF transmembrane conductance regulator (CFTR), develop CF-related diabetes (CFRD) with most patients exhibiting insulin insufficiency." (PMID 25025956, 2014). "In addition, the consistent features between nasal polyps/CRSwNP and cystic fibrosis, a common genetic disorder caused by mutations in the CFTR gene, provides extra evidence that genetically determined alterations of sinus mucosal immunology contribute to the development of CRS." (PMID 25379119, 2014). "The F508del mutation of the cystic fibrosis transmembrane conductance regulator (CFTR) is the most common cause of cystic fibrosis." (PMID 24801204, 2014). "For example, different mutations causing loss of function in CFTR can cause varying levels of severity of cystic fibrosis." (PMID 24456648, 2014).
cystic fibrosis (continued). "Interestingly, low-quality oocytes secreted monoubiquitin as well as several proteins implicated in human disease, such as dystrophin (DMD) and cystic fibrosis transmembrane conductance regulator (CFTR), two proteins implicated in muscular dystrophy, and cystic fibrosis, respectively." (PMID 24804254, 2014). "Two severe CFTR mutations (CFTRsev) cause complete loss of CFTR function and result in cystic fibrosis, a severe genetic disorder affecting sweat glands, nasal sinuses, lungs, pancreas, liver, intestines, and male reproductive system." (PMID 25033378, 2014). "Mutations in the CFTR gene cause the reduction of CFTR expression or abnormalities in its function, thereby resulting in cystic fibrosis, a genetic disease." (PMID 24653706, 2014). "We report a classic cystic fibrosis boy with a large deletion of exons 4–11 in the cystic fibrosis transmembrane conductance regulator (CFTR) gene on one allele and p.Phe508del in exon 10 on the second allele." (PMID 24649380, 2014). "Cystic fibrosis is a lethal autosomal recessive disorder as a result of mutations in the CF transmembrane conductance regulator (CFTR) gene, a cAMP-dependent chloride channel expressed on the apical side of epithelial cells." (PMID 24894806, 2014). "A girl was diagnosed with cystic fibrosis at birth, with repeatedly positive sweat tests and homozygous F508del mutations of her CF transmembrane conductance regulator (CFTR) gene." (PMID 24438707, 2014). "CF is associated with defects of a single gene, the cystic fibrosis transmembrane conductance regulator (CFTR) gene which encodes the chloride channel of the same name." (PMID 26237387, 2014). "Cystic fibrosis is caused by mutations in the gene encoding the CF transmembrane conductance regulator (CFTR) and results in altered ion transport regulation across epithelial membranes." (PMID 24758489, 2014). "CF is caused by mutations in the cystic fibrosis transmembrane conductance regulator (CFTR) gene, encoding an anion channel expressed in epithelial and other tissues." (PMID 24608905, 2014). "Cystic fibrosis transmembrane conductance regulator (CFTR) gene mutations have been identified as the cause of cystic fibrosis, a disease associated with DB and impaired survival due to respiratory insufficiency in most cases." (PMID 25310716, 2014). "Patients with cystic fibrosis (CF, caused by CFTR gene mutation) suffer from recurrent lung infection and inflammation manifested by higher neutrophils and other inflammatory profiles and lower lipoxin A4 levels in the lung." (PMID 24671173, 2014). "Nasal potential difference (NPD) and intestinal current measurement (ICM) are functional CFTR tests that are used as adjunctive diagnostic tools for cystic fibrosis." (PMID 25280757, 2014). "Genetic mutations that reduce CFTR-mediated anion conductance (Ganion = nPOγ ) cause cystic fibrosis." (PMID 24520399, 2014). "Mutations in the cystic fibrosis transmembrane conductance regulator (CFTR) cause recurring bacterial infection in CF patients' lungs." (PMID 25313718, 2014). "Cystic fibrosis is caused by mutations in the CF transmembrane conductance regulator (CFTR) gene, with most of the mortality given by the lung disease." (PMID 24894806, 2014). "Cystic fibrosis is a fatal genetic disorder caused by mutations in the CF transmembrane conductance regulator (CFTR) gene that primarily affects the lungs and the digestive system, and the current drug treatment is mainly able to alleviate symptoms." (PMID 25484921, 2014). "Cystic fibrosis is a common and deadly inherited disease, caused by mutations in the CFTR gene that encodes a cAMP-activated chloride channel." (PMID 25184794, 2014). "Cystic Fibrosis is an autosomal recessive disorder caused by a mutational error in the Cystic Fibrosis Transmembrane Conductance Regulator (CFTR) gene and its associated protein." (PMID 25413892, 2014).
cystic fibrosis (continued). "Pigs expressing either null alleles or the common F508del mutation in the cystic fibrosis transmembrane conductance regulator (CFTR) gene closely recapitulate human CF, including lung disease." (PMID 24691380, 2014). "Cystic fibrosis is an autosomal recessive disorder caused by mutations in the CF conductance transmembrane regulator (CFTR) gene." (PMID 24649380, 2014). "For example, over 1500 different mutations in the cystic fibrosis transmembrane conductance regulator (CFTR) gene have been identified in cystic fibrosis patients." (PMID 25183965, 2014). "Cystic fibrosis is a genetic disorder characterized by a mutation in the gene encoding the cystic fibrosis transmembrane conductance regulator (CFTR)." (PMID 28344236, 2014). "Cystic fibrosis is caused by mutations in the CF transmembrane conductance regulator (CFTR), a channel that normally transports anions across epithelial cell membranes." (PMID 24434788, 2014). "Cystic fibrosis is an autosomal recessive disease caused by mutations in the cystic fibrosistransmembrane regulator (CFTR) gene." (PMID 25356347, 2014). "Cystic Fibrosis is an autosomal recessive genetic disorder resulting from mutations of the Cystic Fibrosis Transmembrane Conductance Regulator (CFTR) gene." (PMID 23977293, 2013). "Cystic Fibrosis is an autosomal recessive disorder caused by mutations within the CF transmembrane conductance regulator (CFTR) gene." (PMID 24344776, 2013). "Cystic fibrosis is a genetic disease caused by mutation of the cystic fibrosis transmembrane conductance regulator (CFTR) gene." (PMID 23737977, 2013). "Cystic fibrosis is a human genetic disorder caused by mutations in the cystic fibrosis transmembrane conductance regulator (CFTR) gene." (PMID 24451123, 2013). "Cystic fibrosis is an autosomal recessive disease associated with a single gene - the cystic fibrosis transmembrane conductance regulator (CFTR)." (PMID 23446051, 2013). "Hyperactivity of these epithelial sodium channels due to loss of CFTR-mediated inhibition in patients with CF leads to some of the symptoms present in cystic fibrosis due to hyperabsorption of sodium resulting in airway dehydration." (PMID 25667824, 2013). "Similarly, almost 2,000 variants in the CFTR gene are associated with cystic fibrosis." (PMID 25411643, 2013). "Genotype-phenotype studies revealed that the risk of P. aeruginosa infection in CF patients depends on the severity of the mutations in cystic fibrosis transmembrane conductance regulator (CFTR) gene." (PMID 23776608, 2013). "Cystic fibrosis is a fatal autosomal recessive genetic disorder caused by loss-of-function mutations in the CFTR gene, which encodes the CFTR protein (CF transmembrane conductance regulator)." (PMID 23982976, 2013). "Cystic fibrosis is caused by mutations in the cystic fibrosis transmembrane conductance regulator (CFTR) gene, which encodes an anion channel." (PMID 23732645, 2013). "Cystic Fibrosis is the most common autosomal recessive disorder in Caucasian populations, caused by mutation in cystic fibrosis transmembrane conductance regulator (CFTR) gene." (PMID 24106596, 2013). "In this study we investigated the effects of the Cystic Fibrosis Transmembrane conductance Regulator (CFTR) gene variants on the composition of faecal microbiota, in patients affected by Cystic Fibrosis." (PMID 23613805, 2013). "Cystic fibrosis is a common genetic disorder resulting from mutations in the cystic fibrosis transmembrane conductance regulator (CFTR) gene." (PMID 23922647, 2013). "Cystic fibrosis is a genetic disorder that results from mutations in the CF transmembrane conductance regulator gene." (PMID 23533140, 2013). "Instead, in PBMC from cystic fibrosis patients, calpain activity is expressed at aberrant levels causing the massive removal of F508del-CFTR from the cell surface." (PMID 23785472, 2013).
cystic fibrosis (continued). "Cystic fibrosis is caused by mutations affecting a polytopic integral membrane protein, termed Cystic Fibrosis Transmembrane-conductance Regulator (CFTR) functioning as a phosphorylation stimulated, ATP-dependent anion channel." (PMID 24058532, 2013). "Mutations in the CFTR gene lead to Cystic Fibrosis –an autosomal recessive disease with majority of the morbidity and mortality resulting from airway infection, inflammation, and fibrosis." (PMID 23671668, 2013). "Mutations in the CFTR gene lead to Cystic Fibrosis –the most common fatal genetic disorder in Caucasians." (PMID 23671668, 2013). "CF is caused by genetic mutations in the Cystic Fibrosis Transmembrane conductance Regulator (CFTR) gene that encodes for an ATP-regulated ion-channel, which is expressed in many tissues." (PMID 23497303, 2013). "Mutations in the gene encoding the cystic fibrosis transmembrane conductance regulator protein (CFTR) cause cystic fibrosis, the most common life-shortening genetic disease among Caucasians." (PMID 24086355, 2013). "Perhaps the best known of these is cystic fibrosis airway disease, in which a mutation in the cystic fibrosis transmembrane conductance regulator (CFTR) impairs the clearance of mucus from the lungs and airways." (PMID 23372732, 2013). "Although most individuals with cystic fibrosis develop progressive obstructive lung disease, disease severity is highly variable, even for individuals with similar CFTR mutations." (PMID 23483918, 2013). "The patient we report of was diagnosed with cystic fibrosis in his first year of life, after a homozygous mutation in the cystic fibrosis transmembrane conductance regulator (CFTR) gene (p.F508 del) was found." (PMID 25667824, 2013). "CF shows an autosomal recessive pattern of inheritance, which is caused by mutations in Cystic Fibrosis Transmembrane Regulator (CFTR) gene." (PMID 23758905, 2013). "Cystic fibrosis lung disease is caused by mutations in the cystic fibrosis transmembrane conductance regulator (CFTR) gene and is the most common genetic form of chronic obstructive pulmonary disease (COPD)." (PMID 23991177, 2013). "CF is due to mutations in the gene on chromosome 7 that encodes an amino acidic polypeptide named CFTR (cystic fibrosis transmembrane regulator)." (PMID 24171010, 2013). "Cystic fibrosis is an autosomal recessive disorder where mutations in the CF transmembrane conductance regulator lead to altered ion flux and the reduction of fluid covering the surface of airway epithelial cells." (PMID 23573242, 2013). "While the goal of neonatal screening is to identify infants with two CFTR mutations, that lead to the classical form of cystic fibrosis, some infants will be diagnosed as CF carriers, having only one CFTR mutation." (PMID 22302635, 2012). "The lack of phenylalanine 508 (ΔF508 mutation) in the cystic fibrosis transmembrane conductance regulator (CFTR) Cl− channel represents the most frequent cause of CF, a genetic disease affecting multiple organs such as lung, pancreas, and liver." (PMID 23060795, 2012). "Cystis fibrosis is a fatal autosomal genetic disorder caused by mutations in the cystic fibrosis transmembrane conductance regulator (CFTR) gene." (PMID 24049649, 2012). "CF is an autosomal recessive disease resulting from the inheritance of a mutant allele of the gene for cystic fibrosis transmembrane conductance regulator (CFTR) from each parent." (PMID 22883684, 2012). "CF occurs due to mutations in the gene CFTR (“Cystic Fibrosis Transmembrane Conductance Regulator”) located in the 7q3.1 region, which encodes the CFTR protein." (PMID 23050589, 2012). "Cystic fibrosis, an autosomal recessive genetic disease affecting more than 70,000 people worldwide, is caused by mutations in the CF transmembrane conductance regulator gene." (PMID 22412992, 2012).